LAMP1 (lysosome associated membrane protein 1)
Diseases named in the same sentence as LAMP1 in open-access papers (continued):
Sharing a sentence is not in itself a finding about the gene and the disease.
infection (continued). "Consistent with a block in endosomal maturation, LAMP1-association with LdCVs was rarely observed on LdCVs at one hour post-infection." (PMID 28317932, 2017). "For this purpose, cells were labeled using anti-β1-integrin antibodies following infection of a fusion construct of LAMP-1 (lysosomal-associated membrane protein-1) and Tag-RFP (red fluorescent protein)." (PMID 29108253, 2017). "In scrambled siRNA treated cells, we observed minimal association of live Y. pestis with Lamp1 (<25%) at 20 and 80 min post-infection, indicating limited association between the YCV and lysosomes at these time points." (PMID 26495854, 2015). "At 20 min post-infection, Lamp1 associated with ~55% of YCVs in Rab1b siRNA treated cells, and was maintained at this elevated level at 80 min post-infection." (PMID 26495854, 2015). "As observed for YCV acidification, there was a significant increase in the association between Lamp1 and paraformaldehyde killed Y. pestis (>60%), supporting an active avoidance of lysosomal fusion by Y. pestis during macrophage infection (p≤0.001)." (PMID 26495854, 2015). "In BEAS-2B cells, nearly all Msm were associated with Lamp1 at early and late time points, while Lamp1-associated Mtb compartments significantly decreased from 80.5+/−4.4% at 4 hrs following infection to 58.1+/−2.6% at 18 hrs following infection (p<0.01)." (PMID 24828674, 2014). "In contrast, 81% of LC3-associated 188SLO- GAS co-localized with LAMP-1 at 1 h post infection, 72% at 3 h post-infection, and 75% at 6 h." (PMID 23762025, 2013). "During the first 8 hours of infection, 100% of internalized parasites were associated to LAMP-1, indicating they were still inside the parasitophorous vacuole." (PMID 23785540, 2013). "As with PV, infection with either HRV-2 or HRV-14 caused a co-localization of LAMP1 with punctate GFP-LC3 in MCF-7 cells." (PMID 21994795, 2011). "Between 30 and 60 minutes post-infection, there was a decrease in the number of LAMP-1 associated bacteria (and in agreement with kinetics observed previously), which is indicative of bacteria escaping the phagosome." (PMID 21698237, 2011). "Infection with the ΔS strain did cause some colocalization between LAMP1 and the bacteria, but it was much less than in ΔRΔS, where most intracellular bacteria are completely engulfed in LAMP1+ lysosomes." (PMID 40506485, 2025). "Additionally, while infection with EPEC-ΔespZ* caused a concomitant increase in PI uptake and Lamp-1 surface expression per cell, infection with EPEC-ΔespZ*/pEspZ resulted in significantly lower levels of the measured parameters." (PMID 38038448, 2023). "Iterative haploid genetic screens for host permissivity factors for the infection of cells by LASV uncovered additional host genes required for glycosylation of α-DG and identified a key missing host cell receptor lysosomal associated membrane protein 1 (LAMP1) for infection." (PMID 35235462, 2022). "It was shown that parasites from both strains increased their intracellular growth in LAMP-deficient cells (LAMP1/2−/−), releasing a significantly higher number of trypomastigote forms at the end of a single intracellular cycle, when compared to infections on wild-type (WT) cells." (PMID 35071040, 2021). "Two hours after infection, LAMP-1 association can be found in approximately 83% of BCVs." (PMID 29184543, 2017). "We found that delivery of exogenous LFn-NADase to the cytosol of GAS-infected OKP7 cells reduced the co-localization of 188 G330D with the lysosomal marker LAMP-1 (Lysosomal–Associated Membrane Protein 1) by 4-fold, from 41% to 10% at 6 h of infection (P<0.001)." (PMID 26938870, 2016). "After 1 h infection pulse, we removed all extracellular bacteria by lysostaphin digestion for 30 min in order to avoid bacterial overgrowth in the medium, which may cause host cell death and immunolabeled for LAMP-1, LC3 or lipoteichoic acid." (PMID 33796486, 2021).
infection (continued). "To test definitively whether autophagy was necessary for the targeting of ubiquitin-associated WT Mm to LAMP-1 positive vacuoles, we assessed infection of Atg5−/− mouse embryo fibroblasts, since Atg5 is a required component of the pathway for autophagosome formation." (PMID 19436699, 2009). "At 48 h post-infection, untreated wild-type BCVs showed low colocalization with LAMP-1, high colocalization with the ER marker calnexin, and minimal association with p62, consistent with maturation into ER-derived replicative BCVs." (PMID 41542404, 2026). "This decrease likely reduced LAMP1+ lysosome size as infection inhibits autophagosome-lysosome fusion." (PMID 40503889, 2025). "FTN_0096 mutant was found within acidic compartments marked by LysoTracker during the initial phases of infection (2–6 h), and the mutant also localized with the lysosomal marker LAMP-1 during the later stages of the infection (12–48 h post-infection)." (PMID 40748985, 2025). "The fact that NEDD9 colocalized with bacteria-containing phagosomes including lysosomal marker LAMP1, as well as with pFAK upon ST infection and was downregulated via lysosomal degradation suggests a regulatory function in macrophage defense against bacteria." (PMID 40506423, 2025). "In IPEC-J2 cells, miR-215 mimic transfection during infection resulted in a significant reduction in genes coding for autophagy-related markers, including LC3B, SQSTM1 (sequestosome-1, p62) and lysosomal marker LAMP1 (Lysosomal-associated membrane protein 1)." (PMID 39943201, 2025). "We observed increased co-localization of FTH1 with the lysosomal marker LAMP1 after PRV-GFP infection by using confocal microscopy." (PMID 40891826, 2025). "In the case of wild-type infection, only a few numbers of bacteria showed colocalization with LAMP-1 in 27–33% of infected cells." (PMID 40748985, 2025). "On the other hand, the large numbers of FTN_0096 mutant were observed with LAMP-1 in 70–79% cells at 2, 6, 12, and 24-h post-infection." (PMID 40748985, 2025). "To identify the nature of this suspected vacuoles, we next performed LC3 and LAMP1 labeling 7–10 h post-infection by WT and mutant strains." (PMID 40824038, 2025). "In the case of infection with the wild-type strain, only a few numbers of bacteria showed colocalization with LAMP-1 in 27–42% of the cells." (PMID 40748985, 2025). "The results showed that most pro-inflammatory markers, such as granzyme, Lamp1, Ifng, Prf1, Ccl5, Emoes, and Id2 transcription, increased after infection." (PMID 41459157, 2025). "This is indeed what we observed: metformin increased phagosome maturation as evidenced by an increased acquisition of the late endosomal/lysosomal marker, LAMP1, to Mav-phagosomes 3 days post infection, and this effect was reversed by MT." (PMID 39737195, 2024). "The level of LAMP1 increased during ΔPldA infections compared to WT and ΔPldA-in infections, suggesting autophagosomes in ΔPldA infection are directed toward the autolysosomal pathway." (PMID 39369445, 2024). "In the TA6 cell line after infection, colocalization of the spike protein and LAMP1 signals within vesicle-like structures was detected, suggesting localization in endolysosomes." (PMID 39625789, 2024). "Infection of the cells with the ΔsidC/sdcA L. pneumophila strain led to a significantly higher portion of LAMP1-positive LCVs (36%) than the wild-type infection." (PMID 38836877, 2024). "Although the subcellular localization pattern of pEP153R shows a huge difference between infection and transfection, LAMP1 and LAMP2 still colocalized with pEP153R gathered in viral factories." (PMID 39451547, 2024). "Despite the infection conditions, LAMP1 and ATP6V1B2 MFI of AM remained the highest among the lung phagocyte subsets." (PMID 38701094, 2024). "Although 1° infection leads to a small increase in LAMP1 staining intensity, 2° infection increases it even more." (PMID 38956024, 2024).
infection (continued). "Infection with either EPEC1/pEspZ, or EPEC2, resulted in a significant loss in surface Lamp-1 and PI nuclei staining, suggesting that translocated EspZ inhibits the EPEC1-evoked LE and lytic cell death." (PMID 38038448, 2023). "On the other hand, we verified the highest amount of colocalization between α3 integrin and LAMP-1, indicating the presence of α3 integrin in late endosomes/lysosomes at the 16 h point of infection." (PMID 37755020, 2023). "A. insuavis AC047 also localized in a LAMP-1-rich AcV within THP-1 macrophages early after infection, although cytotoxicity compounded to the difficulty to kill extracellular bacteria precluded late-stage analyses." (PMID 37598340, 2023). "In general SIFs are formed at later hours of infection by fusion of SCV with late endocytic compartments carrying membranes enriched in glycoprotein LAMP1." (PMID 37773952, 2023). "We detected significantly increased colocalization of LAMP-1 with M. tb in CREB-inhibited MDMs compared to control MDMs at 2h post-infection." (PMID 37000865, 2023). "For this assay, a period of 16 h of fungal-epithelial cell incubation was chosen because it was the longest period of infection with detectable levels of α3 integrin protein and with the highest colocalization between α3 integrin and LAMP-1." (PMID 37755020, 2023). "In EPEC-ΔespZ*-infected cells, the surface Lamp-1 staining is spread over the entire infected cell surface, with minor accumulation at infection sites." (PMID 38038448, 2023). "LC3b protein levels were minimal in non-infected HAE, suggesting a low basal rate of autophagy while Lamp-1, LC3b-I, and LC3b-II expression varied across donors and time points during RV-C15 infection." (PMID 34995322, 2022). "Altogether, these data suggest that a subset of internalized E. faecalis traffic rapidly through early endosomes and reach late endosomal compartments as early as 30 min post-infection and LAMP1+ late endosomal compartments by 4 hpi." (PMID 35390107, 2022). "LisCVs arise after several days of infection, after transitioning of bacteria through a cytosolic state, and exhibited lysosomal features (acidic pH, LAMP1+, cathepsin D+)." (PMID 35007292, 2022). "Following a 24-h infection period, analysis of acceptor cells indicated that a majority of fibrils co-localized with LAMP1 (< 30%), while smaller amounts of fibrils co-localized with EEA1 (3%) and Vamp3 (< 30%)." (PMID 35909452, 2022). "We quantified the intracellular phenotype of SPA in comparison to STM after infection of HeLa LAMP1-GFP cells using live-cell imaging." (PMID 35381053, 2022). "At pH 5.0, where fusion is LAMP1-dependent, and in the presence of cell-surface LAMP1, both 25.10C and 36.1F neutralize infection (right)." (PMID 35613585, 2022). "Biochemical evidence defined a pH-regulated receptor-switching mechanism for LASV entry whereby virus binds α-DG at neutral pH, but as endosomes become progressively acidified, GP dissociates from α-DG and binds LAMP1, leading to productive infection." (PMID 35235462, 2022). "To understand if blocking the GP-LAMP1 interaction is the primary mechanism of neutralization for GPC-A antibodies, we investigated the ability of 25.10C and 36.1F to neutralize infection by rVSV-LASV-GP in LAMP1-dependent and -independent manners." (PMID 35613585, 2022). "Infection of iPSC-derived astrocytes by α-synuclein oligomers led to co-localization between the lysosomal marker LAMP-1 and oligomers 3 days post-exposure." (PMID 35909452, 2022). "For both LCMV and LASV, sialylation of the lysosomal host factor at a specific N-linked glycosylated residue by ST3GAL4 is required for infection, N104 in the case of CD164 and LCMV and N76 in the case of LAMP1 and LASV." (PMID 35235462, 2022). "In contrast, when LAMP1 is knocked out, infection of ppVSV-LI decreases considerably relative to ppVSV-LIV, indicating that LI-GP is more dependent on LAMP1 for efficient viral entry than LASV-LIV." (PMID 35730904, 2022).
infection (continued). "At late stages of infection, we detected an enrichment of the lysosomal protein LAMP1 at the membrane compartments together with the structural transmembrane proteins of SARS-CoV-2." (PMID 34995113, 2022). "LAMP1 was detected on ACVs from 2 to 48 h of infection, but only a small percentage of ACVs were positive for lysotracker at the late stages of the infection, suggesting that this strain is inhibiting acidification or lysosomal fusion." (PMID 35103489, 2022). "Co-localization of p62/SQSTM1, ATG16, Rab5, Rab7a, and lysosomal-associated membrane protein 1 (LAMP1) with the LC3 protein were also observed, which confirmed that phagosome maturation occurs during infection including fusion with maturity or late endosomes." (PMID 35269494, 2022). "When LAMP1 is knocked out, ppVSV-LI infectivity is considerably less efficient than infection by ppVSV-LIV." (PMID 35730904, 2022). "Approximately 15 to 60 minutes post infection, lysosomal glycoprotein (Lgp) LAMP-1 is recruited to the SCV membrane." (PMID 34858868, 2021). "LAMP1 knock down in these two cell lines using shRNA resulted in ~2-3-fold reduction of LAMP1 expression and reduced infection." (PMID 34492091, 2021). "After 16 hr post-infection, cells were fixed and immuno-stained with anti-LAMP1 and anti-HA antibodies to reveal the secreted SseJ and the SIFs." (PMID 34061032, 2021). "During the next 60 min (5–6 h post infection), lysosomes (LAMP1-GFP) progressively translocated from the cytoplasm and fused to the phagosome containing spores at a fusion rate of 11.85 ± 0.45 lysosomes/minute." (PMID 34200399, 2021). "After 16 hr post-infection, cells were fixed and immuno-stained with anti-LAMP1 antibody to reveal the SIFs." (PMID 34061032, 2021). "Next, we followed the intracellular fate of WT S. aureus and the Δpsmαβ strain upon infection of EA.hy926 cells by immunostaining for the autophagy marker LC3 and lysosome-associated membrane protein 1 (LAMP-1) at different time points p.i.." (PMID 33843450, 2021). "The percentage of bacteria that colocalized with the endosomal/lysosomal marker LAMP-1 increased throughout infection, from 84% at 3 hpi to 99% at 48 hpi." (PMID 33901267, 2021). "We therefore evaluated the association of MFN2 with late-endosomal protein Rab7 and lysosomal protein LAMP1 in macrophages in the context of infection." (PMID 33972668, 2021). "To evaluate Salmonella existing within these compartments, we monitored WT and SACM1L KO cells co-expressing GFP-LC3 (marking autophagosomes) and LAMP1-mCherry (marking SCVs) by live cell imaging for 6 h post-infection." (PMID 34320354, 2021). "The effect on infection was more pronounced in A549 cells expressing lower endogenous levels of LAMP1." (PMID 34492091, 2021). "We therefore quantified the percentage of bacteria associated with (i) the late endosomal marker LAMP-1, (ii) the pH-sensitive Dye Lysotracker Red (LTR) or (iii) the autophagosome marker LC3B, after 24 h of infection." (PMID 33720986, 2021). "Our findings indicated that Ms3091-eGFP pretreated with anti-Rv3091 antibodies mainly colocalized with the LAMP-1 marker, indicating that Ms3091-eGFP is enclosed in the phagosome after 24 h of infection." (PMID 33042041, 2020). "Mutant S. Typhimuriumstrains that fail to cluster near the Golgi at 8 hours-post infection in epithelialcells have lower frequencies of LAMP1+-tubule extension and impairedintracellular replication." (PMID 32584855, 2020). "Confocal microscopy analysis showed that H-1PV co-localised with EEA1, Rab7 and LAMP-1 markers during infection." (PMID 33096814, 2020). "Accordingly, J774A.1 infected with PA−Sia/PA+Sia were fixed at 20, 40, and 60 min after infection, permeabilized and stained for early endosomal (Rab5), late endosomal (Rab7) and lysosome specific (LAMP1) markers, respectively." (PMID 32184783, 2020).
infection (continued). "At 2 h post-infection (p.i.), samples were stained for LAMP1 to visualize lysosomes and with DAPI to visualize the nucleus, imaged, and analyzed for object-based colocalization." (PMID 33232373, 2020). "Under the NAM treatment, 61 and 74% of intracellular GAS was colocalized with LAMP-1 at 3 and 5 h of infection, respectively." (PMID 32117141, 2020). "Infected HeLa cells were fixed at8 hours post-infection and immunolabeled with an anti-LAMP1 antibody to labelLAMP1-positive compartments (SCVs) and tubules (SIFs) andanti-Salmonella antibody to label intracellularS." (PMID 32584855, 2020). "Similar to previous findings from mammalian host cell systems, A. baumanni resided in lysosomal marker LAMP-1 or cathepsin D-positive compartments at later time points post-infection (24 h.p.i.)." (PMID 32528902, 2020). "Lamp1 mediates the fusion of autophagosome with lysosomes, and is closely related to autophagy and infection immunity." (PMID 31425535, 2019). "At 24 h post-infection, the presence of LAMP-1 on phagosomes harboring L. donovani promastigotes LV9 remained very low, as was also the case for phagosomes containing L. braziliensis M2903, RR410, and RR418." (PMID 31555609, 2019). "The ratio of Δslt mutant that colocalized with LAMP-1 increased from 10% to 20% 12–24 h after infection." (PMID 31877174, 2019). "In this study, we routinely used HeLa cells constitutively expressing LAMP1-monomeric enhanced green fluorescent protein (meGFP) as host cells for infection." (PMID 31239375, 2019). "LAMP-1 dependence of LASV entry was assessed by infection with recombinant VSV pseudotypes bearing either LASV GP or the GP of LCMV clone 13 that is LAMP-1 independent." (PMID 30914516, 2019). "For strains RR418 and M8401, their ability to replicate in BMM correlated with their capacity to impair the phagosomal recruitment of LAMP-1 and acidification during the early phases of infection." (PMID 31555609, 2019). "Infection of M. marinum that replicates in the LAMP1-positive compartment is compromised in a FLOT ortholog vacuolin B mutant of Dictyostelium amoebae, suggesting an important role of host FLOT during mycobacterial intracellular infection." (PMID 30914515, 2019). "We found a significant decrease in the presence of LAMP-1 in the EVs derived after infection, compared with the control." (PMID 31847332, 2019). "(A) The percent of bacteria enclosed in a LAMP-1 positive vacuoles 3 hr after a synchronized infection with extracellular bacteria." (PMID 31017571, 2019). "Accordingly, a higher concentration of NH4Cl was needed to block LASV GPC-mediated infection in WT (Lamp1-positive) cells." (PMID 29295909, 2018). "In other words, LASV infection in Lamp1 KO cells should be more sensitive to the effects of NH4Cl than infection in WT (Lamp1-positive) cells." (PMID 29295909, 2018). "Previous studies of the role of LAMP1 in infection indicate that acidification of the LE/LY reduces the affinity of LASV for α-DG, enhances binding to LAMP1, and promotes virus membrane fusion." (PMID 30265711, 2018). "The timely recruitment and dissociation of LAMP-1 to BCPs during early infection has been proven to be critical for the subsequent lysosome-mediated killing activity that mainly contributes to the final outcome of Brucella infection." (PMID 30186773, 2018). "Trafficking of Salmonella during MDM infection has been shown to involve the acquisition of the late endosomal/lysosomal membrane protein LAMP1." (PMID 29538403, 2018). "Using a photo-reactive analog that retains antiviral activity as a probe, we identified the inhibitor target as lysosome-associated membrane protein 1 (LAMP1), a host factor that binds to the LASV glycoprotein (GP) during infection." (PMID 30265711, 2018). "As observed for YCV acidification, Y. pestis actively inhibits lysosomal fusion, with only ~20% of YCVs colocalizing with LAMP-1 during the first 80 min of infection." (PMID 29463656, 2018).